TMEM210 (transmembrane protein 210)
Tractability: Antibody: UniProt predicts a signal peptide or a membrane-spanning region.
Gene: Protein-coding gene on chromosome 9 (137,170,858 to 137,172,056, reverse strand). Ensembl gene ENSG00000185863.
Subcellular location: Membrane; Cytoplasmic vesicle, secretory vesicle, acrosome
Gene Ontology:
Cellular component: acrosomal vesicle; membrane
Genetic constraint (gnomAD): Loss-of-function variants: 7 observed, 9.53 expected, observed/expected ratio (o/e) 0.73, 90% interval 0.42 to 1.37. That is too few expected variants to judge how well the gene tolerates losing a copy. Missense variants: 185 observed, 181.83 expected, observed/expected ratio (o/e) 1.02, 90% interval 0.9 to 1.15. Synonymous variants: 79 observed, 75.66 expected, observed/expected ratio (o/e) 1.04, 90% interval 0.87 to 1.26.
Homologues: Orthologues: chimpanzee TMEM210 (98% identical), macaque TMEM210 (92% identical), mouse Tmem210 (69% identical), rat Tmem210 (67% identical), guinea pig TMEM210 (53% identical).